EGFR (epidermal growth factor receptor)
Diseases named in the same sentence as EGFR in open-access papers (continued):
Sharing a sentence is not in itself a finding about the gene and the disease.
cancer (continued). "Both EGFR-mut and KRAS-mut cancers are now being treated with targeted therapy." (PMID 36612014, 2022). "In cancer cells, H2O2 may regulate EGFR and mitogen-activated protein kinase (MAPK) signaling that contribute to redox protein-mediated cancer progression." (PMID 35269445, 2022). "Epidermal growth factor receptor is a known regulator of cell proliferation, and sialylation can alter proliferative signaling cascades in different cancers both in the presence or absence of proliferative stimuli." (PMID 35157848, 2022). "Moreover, the palmitoylation or depalmitoylation of proteins, including EGFR, RAS, PD-1/PD-L1, etc., are tightly in connection with the progression of tumors and they determine the sensitivity of cancer treatment." (PMID 35637973, 2022). "The role of the activation of EGFR, Wnt/beta-catenin, Hippo, TGF-beta, and JAK/STAT cascades in CAFs in relation to the chemoresistance and invasive or metastatic behavior of cancer cells has strengthened the concept that CAFs should be included as a target for therapy in solid tumors." (PMID 35326670, 2022). "Although previous studies concluded that S100A4 could interact with the following membrane receptors, including RAGE, EGFR, ERBB2, TLR4, and IL10R, these findings were derived from the nervous system or cancer-related studies." (PMID 36361563, 2022). "A similar process has been reported with targeted BRAF inhibition in BRAF mutant cancers, where deactivation of the negative feedback mechanism induces EGFR-mediated activation of RAS." (PMID 36189421, 2022). "Furthermore, VV spread is dependent on epidermal growth factor receptor (EGFR) signalling, a pathway that is activated in most cancers." (PMID 36140243, 2022). "MiRNA-let-7c-5p, the miRNA studied in our research, has been widely reported in different cancer types, it can mediate the pathogenesis progression of NSCLC by targeting ITGB3 and MAP4K3 31, and promote the sensitivity of LUAD cells to EGFR-TKIs by inhibiting the WNT pathway." (PMID 36046641, 2022). "HNK controls various intracellular signaling pathways involved in cancer, including those related to nuclear factor kappa B (NF-κB), signal transducers and activators of transcription 3 (STAT3), epidermal growth factor receptor (EGFR), and mammalian targets of rapamycin (mTOR)." (PMID 35845599, 2022). "In addition to the clinical markers (i.e., EGFR, HER2), the folate receptor is a popular choice for cancer imaging." (PMID 34976579, 2022). "For example, Seifert and colleagues engineered liposomes able to target epidermal growth factor receptor (EGFR, overexpressed on a variety of cancers) by functionalizing the liposomes with an EGFR-specific single-chain Fv molecule (EGFR scFv) and TRAIL (immune-LipoTRAIL)." (PMID 36291908, 2022). "It was noted that the Target-NPs (with EGFR-targeting peptide) had a better anti-cancer effect than the non-Target-NPs (without EGFR-targeting peptide)." (PMID 36421144, 2022). "The epidermal growth factor receptor (EGFR) is a transmembrane cell surface protein belonging to HER family tyrosine kinase receptors that plays a pivotal role in proliferation, migration, survival, and invasion of cancer cells." (PMID 35517713, 2022). "Among these receptors, EGFR and HER2 are both well recognized biomarkers and genuine therapeutic targets of different cancers, but overexpression of HER3 and HER4 may lead to differential prognostic outcomes of cancer patients." (PMID 35269825, 2022).
cancer (continued). "In particular, CDK6 was chosen for the function “pathway in cancer”, ADAM12 for the function “signaling by EGFR”, HDAC4 was selected for the function “regulation of cell differentiation”, and finally Bcl2 for the function “negative regulation of apoptotic processing”." (PMID 36498866, 2022). "Interestingly, previous work on BRAF, EGFR, and HER2 also focused on the length of the β3/αC loop as a determinant of both kinase activation in cancer and inhibitor sensitivity." (PMID 36357385, 2022). "The role of MET in EGFR exon 20 insertion mutant driven cancers has not been investigated and only one patient enrolled in the CHRYSALIS trial was identified to have baseline MET amplification." (PMID 34913823, 2022). "This, without doubt, has highlighted EGFR as an attractive therapeutic target for the treatment of patients with EGFR-expressing cancer." (PMID 36185288, 2022). "Similar to EGFR, FGFR is driver gene playing key roles the development of cancer." (PMID 36426352, 2022). "The cyclic bioconjugate showed preferential uptake by two EGFR-positive cancer cell lines compared with two EGFR-negative counterparts, resulting in significantly higher photocytotoxicity." (PMID 35213974, 2022). "GJB6 was conserved only in EGFR-mut and KRAS-mut cancers while the latter also conserved GJB3." (PMID 36612014, 2022). "Molecules such as epidermal growth factor receptor (EGFR), transforming growth factor (TGF) ß-activated kinase, and small GTPases can facilitate their survival during the metastatic cascade of detached cancer cells." (PMID 36359874, 2022). "The clonogenic cell survival assay consistently demonstrated that rSPINK1 protein induced cancer cell radioresistance in the absence of EGFR Inhibitor III, but not in its presence." (PMID 34747365, 2021). "Our study also supported that patients with low NLR had better survival data in NSCLC patients undergoing EGFR-TKIs treatment, indicating neutrophil as a negative prognostic parameter in cancer patients." (PMID 33542732, 2021). "Finally, it has been shown that EGFR-targeting tyrosine kinase inhibitors (TKIs) also disturb EGFR trafficking in GBM cells and in various other cancer cell types." (PMID 34831480, 2021). "Notably, EGFR and its receptors, including TGFB1, MIF, HBEGF, GRN, COPA, and AREG, were upregulated in cancer cells and fibroblasts." (PMID 34326696, 2021). "Since nanocarriers are able to encapsulate and deliver insoluble small molecules, antibodies, and nucleic acids such as miRNA and mRNA, EGFR-targeting nanocarriers can provide alternative therapeutic opportunities for patients with TNBC and other EGFR-overexpressing cancers." (PMID 34207383, 2021). "Moreover, RABL6A is a potent oncoprotein that controls many druggable cancer targets besides CDK4/6 and MEK, including Myc, PP2A-Akt-mTOR, and receptor tyrosine kinase pathways like VEGFR and EGFR." (PMID 33456709, 2021). "EGFR and HER2 are well-defined therapeutic targets for cancer." (PMID 33796531, 2021). "The EGFR gene is located in the 7p11.2 locus of chromosome 7, and its amplification using fluorescence in situ hybridization (FISH) is routinely used by pathologists to determine diagnoses of cancer patients." (PMID 34771555, 2021). "Aberrations in major signaling pathways, such as epidermal growth factor receptor (EGFR), tyrosine kinases, and molecular pathways that control cancer hallmarks such as angiogenesis, cell cycle, apoptosis, and proteosome regulation, finally result in metastasis." (PMID 33805840, 2021). "Therefore, antigens such as β-catenin, MUC1, EGFR, FGFR, and PDGFR are sufficient targeted therapies for metastatic cancer cells, while E-cadherin is efficient for cancers in primary stages or after metastasis." (PMID 34679012, 2021). "In recent years, the intrinsic mechanisms of metabolism, autophagy, cancer stem cells (CSCs) and epithelial-to-mesenchymal transition (EMT ) have also been confirmed to be correlated with poor progression despite anti-EGFR mAb treatment." (PMID 34663410, 2021).
cancer (continued). "Therefore, the inhibition of the signaling pathways EGFR and VEGF is also a promising technique for cancer chemotherapy." (PMID 34221232, 2021). "In CRC patients, the binding of VEGF/VEGFR results in migration, invasion, and survival of cancer cells, while the binding of EGF/EGFR results in cell proliferation, vascular permeability, and cancer cell survival, all leading to angiogenesis which is one of the main derivers of CRC." (PMID 33440689, 2021). "EGFR is common in ATC patients and antibodies or small molecules based on EGFR immunotherapy can significantly increase the therapeutic effect against this cancer." (PMID 33551680, 2021). "Moreover, the alteration in expression levels of other molecules such, c-MET, RAS/BRAF, EGFR/ERBB2 which are involved downstream, affect cancer cell proliferation and development." (PMID 33777535, 2021). "When ROS levels exceed the self-regulating ability of cancer cells, ROS directly decrease the expression of EGF and EGFR and markedly inhibit the phosphorylation of EGFR; as a result, downstream cell proliferation signaling molecules are inhibited, such as ERK and PI3K/Akt 97-99." (PMID 34405016, 2021). "In addition, specific monoclonal antibodies against EGFR such as cetuximab and panitumumab are FDA approved for various cancer indications." (PMID 34591244, 2021). "NA49 augmented the cell death in EGFR-WT cells when combined with Gef, and depletion of HSP27 diminished these effects, suggesting HSP27 inhibition as a potential chemo-sensitization target for Gef treatment in EGFR-WT cancer cells." (PMID 33925114, 2021). "Despite altered CYLD expression having been observed in various cancers in which EGFR signalling contributed to cancer development and progression, the roles of CYLD in EGFR signalling and response to anti-EGFR therapies remain unknown." (PMID 35008337, 2021). "Other quantitative PCR analysis resulted in elevated expressions of ESR1, EGFR mRNA in cancer samples in comparison with those in non-cancer controls (P < 0.05)." (PMID 34592904, 2021). "Importantly, these are predictive biomarkers for drugs that are currently in use for treating different cancers, such as PARP, ERBB2, EGFR, PIK3CA, mTOR, and Hedgehog signaling inhibitors." (PMID 34575676, 2021). "Thus, analysis of clinical patient data provides evidence of the relevance of our findings in EGFR-positive LUAD, showing that PLK1 is a strong predictor of poor overall survival in LUAD cancer patients." (PMID 34503223, 2021). "Moreover, the cross‐talk between epidermal growth factor receptor (EGFR)‐mediated autophagy and cell death has also been currently utilized for cancer treatment." (PMID 33960631, 2021). "Previous studies have shown that the epidermal growth factor receptor (EGFR) ligands epidermal growth factor (EGF) and transforming growth factor-α (TGF-α) transactivate the GPER promoter and stimulate its expression in cancer cells." (PMID 34773076, 2021). "It is worth pointing out that since proteins within Gene EGFR and Gene HRAS affect multiple cancers as compared to proteins within Gene MAPK3 which are unique to each type of cancer, the cost benefit payoff ratio would be higher for Gene EGFR and Gene HRAS than for Gene MAPK3." (PMID 34764329, 2021). "Fluorescently labeled B-ASOs localized mostly in the cytoplasm and decreased EGFR expression by activating RNase H. Moreover, the B-ASO complexes altered the cancer cell phenotype, decreased cell migration rate, and arrested the cells in the S phase of cell cycle." (PMID 34064412, 2021). "Therefore, determining the most favorable outcomes of combined therapies, including targeting EGFR, EREG, and other driver oncogenic genes in a subpopulation of patients with cancer is crucial." (PMID 34884633, 2021). "Crosstalk between EGFR and other RTKs, such as ErbB-family members, c-Met and Insulin-like growth factor 1 receptor (IGF-1R), are vital in ascertaining the mechanisms of drug resistance in cancer treatment." (PMID 34112110, 2021).
cancer (continued). "The overexpression of the two P2Y1 and P2Y2 receptors might render cancer cells hypersensitive to their extracellular ligands (ADP and ATP or UTP, respectively) as this was reported for other receptors like EGFR." (PMID 34768902, 2021). "In the FISH analysis, EGFR amplification was found in the resistant liver lesions but not in the lung lesions, which suggests that heterogeneous cancer cells emerged with resistant EGFR‐amplified cancer cells in the liver metastases." (PMID 33471376, 2021). "In addition, many other EGFR/HDAC hybrid inhibitors are under investigation preclinically and exhibited promising results against different types of cancer." (PMID 34832959, 2021). "Interestingly, we also found that the upregulation of phospho-AKT appeared to be an adaptive pro-survival of EGFR-mutant NSCLC cells under lysine reduction, which is consistent with the pro-survival role of AKT observed under other stresses in cancer cells." (PMID 33450879, 2021). "Interestingly, targeted therapies such as EGFR inhibitors and CDK4/6 inhibitors can induce a strong reactivation of repeated elements in cancer cells, which results in cell death." (PMID 34071428, 2021). "Small‐molecule inhibitors, such as BRAF and EGFR inhibitors, and immune checkpoint inhibitors (CPI), such as anti‐PD‐1/L1 and anti‐CTLA‐4, have revolutionised cancer therapy." (PMID 34459009, 2021). "The MET signaling pathway can be activated by multiple molecules, plexins, integrins, EGFR, and ERBB2, and the crosstalk between those pathways may contribute to cancer progression and drug resistance." (PMID 34761497, 2021). "Finally, we tested a profile including EGFR and VEGFR2 as targets, due to the interest in them for cancer treatment, and tried again to design out binding to BRAF." (PMID 33530327, 2021). "Furthermore, high‐level amplifications targeting cancer‐critical genes, including the therapeutic targets ERBB2 and EGFR, were also typically homogeneously present within patients, both among multiple metastatic lesions and in the primary tumor." (PMID 33325154, 2021). "Thus, measuring EGFR and HER2 levels in patients with NSCLC has been evaluated to predict the anti-cancer activity of gefitinib (a TKI) due to increased HER2, in patients with EGFR-positive NSCLC." (PMID 33578653, 2021). "Furthermore, the phosphorylation levels of EGFR, ERBB2, GRB2, and SRC were significantly reduced in the PAF-AH 1B2 KD cancer cells as determined by the Luminex assay and western blot data." (PMID 34930255, 2021). "In our study, EGFR shows different express pattern for HPV+ and HPV− cancers." (PMID 34646755, 2021). "When EGFR-negative cancer cell lines Hep G2 and MCF-7 were imaged under dark-field microscope, a low number of AuNRs aggregates with bright signal scatters was observed." (PMID 34683944, 2021). "Similar to other oncogenic RTKs, like EGFR and ALK, distinct FGFR mutants might harbour different signalling dependencies, driving cancer progression by the activation of altered downstream pathways." (PMID 34068816, 2021). "Functionalization of NPs with anti-EGFR antibodies was another solution to transport new non-water soluble anti-cancer compounds." (PMID 33923200, 2021). "As with GBM, nuclear PKM2 has been detected in EGFR-mutant NSCLC cancer cells but not in EGFR wild-type NSCLC cells." (PMID 34439090, 2021). "Indeed, several studies have demonstrated that SHP2 inhibition can overcome resistance to EGFR, HER2, ALK, and MEK inhibitors in multiple cancer models." (PMID 34503119, 2021).
cancer (continued). "In conclusion, based on our findings in the NSCLC cell models and the two independent patient cohorts, targeting cancer progression through DCA treatment, represents a promising strategy to increase the therapeutic effects initiated by conventional treatment like EGFR TKI and ionizing radiation." (PMID 33668151, 2021). "EGFR and HER2 are important receptors that play critical roles in many cancers." (PMID 33917370, 2021). "Further clinical development for systemic treatment was halted due to severe in vivo off‐target toxicities caused by the monovalent human EGF fusion toxin (mono‐EGF‐IT), despite its good in vivo efficacy against EGFR+ cancers." (PMID 33540470, 2021). "Excessive activation of EGFR activates multiple downstream signaling pathways, such as the MEK/ERK/MAPK, PI3K/AKT/mTOR, and JAK1/STAT3/5 signaling pathways), thereby enhancing the tumorigenesis, progression, and metastasis of various cancers." (PMID 33909822, 2021). "Epidermal growth factor receptor (EGFR) and vascular endothelial growth factor receptor (VEGFR) are two extensively studied membrane-bound receptor tyrosine kinase proteins that are frequently overexpressed in many cancers." (PMID 33670650, 2021). "Notably, epidermal growth factor receptor (EGFR) is a receptor tyrosine kinase that is highly expressed in OSCC and is a common target in various cancer types." (PMID 34830778, 2021). "Some reports suggested that EGFR expression can be regulated by HPV E5 protein, while contradicting reports showed that E5 protein does not regulate the expression of EGFR and cancer prognosis." (PMID 34646755, 2021). "EGFR-TKIs have also been validated to activate autophagy in NSCLC and other cancer cells." (PMID 34054543, 2021). "EGFR is a transmembrane receptor for ligands of the epidermal growth factor family extracellular proteins, and activation of EGFR is well-known to enhance the growth of HCC and various other cancers by increasing their invasiveness." (PMID 33952719, 2021). "We hypothesize that the smart combination of CIMAVax-EGF with the established EGFR TKI and ICIs can further contribute to the transition of advanced cancer to a chronic disease, compatible with years of quality life." (PMID 34211836, 2021). "Cho and coworkers (2019) found that miR-21, miR-574-3p, EpCAM, and epidermal growth factor receptor (EGFR) were more highly expressed in exosomal cancer-derived cells than in noncancer cells." (PMID 34940275, 2021). "In live cancer, TGF-β could upregulate the expression of EGFR ligands, which transactivated the EGFR pathway, counteracting its pro-apoptotic response." (PMID 33980265, 2021). "Research has also shown that interaction between epidermal growth factor receptor (EGFR) and NOTCH pathway proteins may function to promote proliferation of cancer cells." (PMID 34012965, 2021). "Notably, four of these proteins (i.e., EGFR, IGF-IR, PDGFRβ and Axl) also showed the highest increase in phosphorylation in cancer tissue samples after denosumab treatment compared to untreated samples." (PMID 34298757, 2021). "Similarly, the network figures for the remaining networks show similar positioning for many important cancer genes: NOTCH1 in liver, NOTCH3 and EGFR in lung are some other examples." (PMID 34115745, 2021). "The connection between osimertinib or EGFR-targeted cancer therapy and DR4 suppression has not been reported." (PMID 33664875, 2021). "Unlike other growth factor receptors, such as EGFR and HER-2, mutations activating the IGF-1R gene have rarely been reported in cancers." (PMID 34359752, 2021). "The data presented here suggests that Rac plays an integral role in the activation of EGFR/HER2 signaling during therapy resistance and that this increase in active Rac levels may promote cancer stem cell maintenance, as well as cell growth and survival." (PMID 34074257, 2021).